PYGO2 (pygopus family PHD finger 2)
Diseases named in the same sentence as PYGO2 in open-access papers (continued):
Sharing a sentence is not in itself a finding about the gene and the disease.
pancreatic cancer (8 papers, 2020 to 2024). "PVT1 can stimulate the Wnt/β-catenin signaling pathways and autophagy through the function of miR-619-5p in the miR-619-5p/autophagy-related 14 (ATG14) and miR-619-5p/pygopus homolog 2 (Pygo2) axes, causing chemo-resistance promotion in pancreatic cancer." (PMID 38559560, 2024). "The lncRNA-PVT1/miR-619-5p/Pygo2/ATG14 axis was shown to be critical for the promotion of gemcitabine chemoresistance of pancreatic cancer." (PMID 35371339, 2022). "Specifically, miR-619-5p has been shown to improve pancreatic cancer sensitivity to gemcitabine by targeting Pygo2 and activating the Wnt/β-catenin pathway." (PMID 35663324, 2022). "For example, PVT1 were found to be upregulated in pancreatic cancer and overcome gemcitabine resistance through sponging miR-619- 5p, leading to upregulation of Pygo2, which is a downstream target of miR-619-5p." (PMID 36266267, 2022). "We also found that the mRNA expression of Pygo2 was much higher in gemcitabine resistant pancreatic cancer cell lines than in control cells." (PMID 32727463, 2020). "We also indicated that PVT1 modulates gemcitabine resistance by the miR-619-5p/Pygo2 and miR-619-5p/ATG14 axes in pancreatic cancer cells." (PMID 32727463, 2020). "Taken together, our data demonstrated that PVT1 functions as a ceRNA to regulate the miR-619-5p/Pygo2 and miR-619-5p/ATG14 axes to improve pancreatic cancer chemoresistance." (PMID 32727463, 2020). "One study found that PVT1/miR-619-5p/Pygo2 and PVT1/miR-619-5p/ATG14 regulatory axes could mediate gemcitabine resistance in pancreatic cancer cells by activating Wnt/β-catenin signaling pathway and autophagy signaling pathway respectively." (PMID 38811958, 2024). "Pvt1 oncogene (PVT1) is upregulated in gemcitabine-resistant pancreatic cancer cell lines, and PVT1 promotes Pygopus family PHD finger 2 (Pygo2) and ATG14 expression; the PVT1/miR-619-5p/Wnt/β-catenin axis promotes cellular autophagy and attenuates resistance to gemcitabine." (PMID 38481525, 2024). "Moreover, upregulated PVT1 can activate Wnt/β-catenin signaling pathway by regulating expression of both Pygo2 and ATG14 and thus promote autophagy related complex in pancreatic cancer." (PMID 35392800, 2022).
hepatocellular carcinoma (6 papers, 2015 to 2025). A malignant tumor that arises from hepatocytes. "Overexpression of Pygo2 enhanced hepatic carcinoma cell invasion and metastasis through reducing E‐cadherin expression." (PMID 31273950, 2019). "Notably, aberrant overexpression of PYGO2 has been observed in various malignancies, including hepatocellular carcinoma, as well as ovarian, breast, cervical, and lung cancers." (PMID 41133538, 2025). "The role of PYGO2 in hepatocellular carcinoma (HCC) is an emerging area of research, particularly due to its involvement in glycosylphosphatidylinositol (GPI) anchor biosynthesis." (PMID 41133538, 2025). "In hepatocellular carcinoma (HCC), Wnt/β-catenin and Myc signaling are upregulated, and the correlative overexpression of nuclear PYGO2 and Myc represent the malignant characteristics of HCC." (PMID 40034933, 2024). "In hepatocellular carcinoma (HCC), elevated PYGO2 expression has been positively correlated with increased tumor size, vascular invasion, and poor tumor differentiation." (PMID 41133538, 2025). "The treatment of hepatocellular carcinoma (HCC) is particularly challenging in cases with complex molecular profiles, such as PIK3CA-positivity and PYGO2-negativity, as observed here." (PMID 41133538, 2025). "Case presentation: In this paper we present a rare case of hepatocellular carcinoma with PIK3CA-positive and PYGO2-negative signaling pathways, several key aspects of the tumor’s behavior, prognosis, and treatment options." (PMID 41133538, 2025). "In a case of hepatocellular carcinoma (HCC) which was PIK3CA-positive and PYGO2-negative, several key aspects of the tumor’s behavior, prognosis, and treatment options can be inferred." (PMID 41133538, 2025).
lung carcinoma (6 papers, 2013 to 2022). "We observed a time-dependent reduction in Pygo2 expression which was associated with a reduced proliferation rate in all of the lung cancer cell lines, especially at time points later than 48 h." (PMID 23865714, 2013). "In addition, it was investigated whether Pygo2 expression correlates with β-catenin expression and is associated with aberrant Wnt pathway activation and cell proliferation in lung cancer." (PMID 24348855, 2014). "Pygo2 overexpression has been identified as an important contributor to abnormal Wnt activation in human lung cancer and has become a putative therapeutic target." (PMID 36398031, 2022). "Pygo2 and β-catenin proteins were also correlatively expressed and colocalized in the nuclei of lung cancer cell lines." (PMID 24348855, 2014). "Western blot analysis was first used to examine the expression of Pygo2 and cytosolic β-catenin proteins in human primary lung cancer tissue samples." (PMID 24348855, 2014). "In conclusion, we propose that Pygo2 is a putative promising therapeutic target for human lung cancer." (PMID 24348855, 2014). "Co-immunofluorescent staining showed that Pygo2 protein accumulated in the nuclei and colocalized with nuclear β-catenin in lung cancer cell lines expressing Pygo2." (PMID 24348855, 2014). "Western blot analysis was also used to examine and compare the expression of Pygo2 and cytosolic β-catenin proteins in human lung cancer cell lines." (PMID 24348855, 2014). "In the ten tissue samples from lung cancer patients examined, upregulation of Pygo2 expression was observed in 90% (9 out of 10) of the tumor samples when compared with their matched normal lung tissues." (PMID 24348855, 2014). "The present study showed that Pygo2 is overexpressed in human lung cancer tissue samples and cell lines." (PMID 24348855, 2014). "Next, the effects of inhibiting Pygo2 expression on the cell survival in human lung cancer cells were studied." (PMID 24348855, 2014). "A significant overexpression of Pygo2 was demonstrated in primary lung cancer tissue samples when compared with their adjacent normal tissues, as well as in the examined lung cancer cell lines." (PMID 24348855, 2014). "Pygo2 expression in fresh human lung cancer tissue specimens and cell lines was examined, as well as the correlation between Pygo2 function and the canonical Wnt pathway in lung cancer cells." (PMID 24348855, 2014). "In this study, we demonstrated that Pygo2 protein levels are significantly higher in lung cancer tissues than in normal lung tissues." (PMID 23865714, 2013). "Pygo2 mediates cancer cell survival and is therefore essential to the malignant tumor phenotype, and also provides a preliminary insight into how Pygo2 overexpression leads to lung cancer." (PMID 23865714, 2013). "Pygo2 protein levels were compared in lung cancer tissues and corresponding normal lung tissues, as well as in A549, SPC-A-1 and LTEP-a-2 lung cancer cell lines." (PMID 23865714, 2013). "Increased expression of nuclear Pygo2 has been reported in 82% of epithelial ovarian cancer tissues, and silencing of endogenous Pygo2 can not only suppress the growth of breast and epithelial ovarian cell lines but also induce apoptosis of lung cancer cell lines." (PMID 25871475, 2015). "Notably, the protein levels of Pygo2 were found to correlate with those of cytosolic β-catenin in the lung cancer tissue samples examined." (PMID 24348855, 2014). "In the present study, the expression of Pygo2 in human lung cancer was examined." (PMID 24348855, 2014). "The current study sought to investigate whether Pygo2 is important in aberrant activation of the Wnt signaling pathway in human lung cancer." (PMID 24348855, 2014). "A small molecule or short peptide strategy blocking interaction between Pygo2 and β-catenin may be preferable in order to generate significant biological activity with minimal toxicity for the treatment of lung cancer." (PMID 24348855, 2014).
lung carcinoma (continued). "Such targeted strategies and agents may also benefit lung cancer patients demonstrating a Pygo2 tumor signature in the future." (PMID 24348855, 2014). "Overall, the results of the present study suggested that Pygo2 may be a good target for the development of therapeutics to treat lung cancer." (PMID 24348855, 2014). "In addition, co-immunofluorescent staining of Pygo2 and β-catenin proteins was performed and confirmed that Pygo2 protein accumulated in the nuclei and colocalized with nuclear β-catenin in lung cancer cell lines." (PMID 24348855, 2014). "Pygo2 and cytosolic β-catenin proteins were correlatively expressed in the lung cancer cell lines (A549, A427, H1299, H460, H1650 and H1703) that were examined, which was consistent with the observation in lung cancer tissue samples." (PMID 24348855, 2014). "Our result also showed that Pygo2 is related to apoptosis of lung cancer cells." (PMID 23865714, 2013). "Furthermore, we knocked down Pygo2 with small interfering RNA (siRNA) in human lung cancer cell lines and investigated its effect on cell proliferation." (PMID 23865714, 2013). "In lung cancer tissues, Pygo2 staining was significantly elevated (P = 0.007, n = 30)." (PMID 23865714, 2013). "Moreover, there was a close correlation between abnormal Pygo2 expression in lung cancer samples and some clinicopathological factors." (PMID 23865714, 2013). "In addition, Pygo2 contributes to the proliferation of lung cancer cells, and regulates the apoptosis and cell cycle of lung cancer cells, indicating that Pygo2 is required for lung cancer cell growth." (PMID 23865714, 2013). "In addition, we revealed that siRNA-mediated Pygo2 depletion inhibited the growth of lung cancer cells." (PMID 23865714, 2013). "Overall, the results suggested that Pygo2 may be a therapeutic target for lung cancer." (PMID 24348855, 2014). "Since aberrant overexpression of Wnt ligands has been previously reported in human lung cancer, the results of the present study suggested that there may be a functional significance of the Pygo2 overexpression in aberrant activation of Wnt signaling in human lung cancer." (PMID 24348855, 2014). "Furthermore, Pygo2 shRNA significantly suppressed lung cancer xenograft models in vivo (P<0.05)." (PMID 24348855, 2014). "In addition, we examined the levels of Pygo2 expression in normal and lung cancer cell lines." (PMID 23865714, 2013). "Furthermore, Pygo2 overexpression correlated with poor prognosis in lung cancer patients." (PMID 23865714, 2013). "We therefore reasoned that Pygo2 may regulate the proliferation of lung cancer cell lines." (PMID 23865714, 2013). "However, the identity of the factors that may participate with Pygo2 to regulate cell cycle progression in lung cancer needs to be further explored." (PMID 23865714, 2013). "Pygo2 was more highly expressed in lung cancer cell lines than in HBE cells, moreover, the levels of Pygo2 in lung cancer cells were similar to lung cancer tissues, as determined by Western blot analysis." (PMID 23865714, 2013). "Of the 168 lung cancer samples, 68.45% of NSCLC samples had moderate (++) to strong (+++) nuclear accumulation of Pygo2 protein." (PMID 23865714, 2013). "In addition, we revealed significant overexpression of Pygo2 in lung cancer cell lines relative to immortal bronchial epithelial cells, which further supports our hypothesis that Pygo2 overexpression characterizes lung cancer malignancy." (PMID 23865714, 2013). "Despite this data, no clinical studies investigating Pygo2 expression in lung cancer have yet been reported." (PMID 23865714, 2013). "Immunohistochemical analysis showed low expression of Pygo2 in normal lung tissues and increased nuclear expression in lung cancer tissues, either with or without perinuclear expression." (PMID 23865714, 2013).
lung carcinoma (continued). "We used small interfering RNA (siRNA) to specifically silence Pygo2, and investigated its effect on cell growth by an 3-(4,5-dimethylthiazol-2-yl)-2,5-diphenyltetrazolium bromide (MTT) assay and flow cytometry analysis in human lung cancer cell lines." (PMID 23865714, 2013). "Pygosus 2 (PYGO2) is a component of the Wnt signaling pathway required for β-catenin/T-cell factor (TCF)-dependent transcription and has been shown to be upregulated in lung cancer both in vitro in non-small cell lung cancer cell lines and in vivo in human primary tumor tissue samples." (PMID 27740511, 2017). "Overall, these results suggested that Pygo2 may be functionally important for β-catenin/TCF-dependent transcriptional activity and aberrant activation of the canonical Wnt signaling pathway in human lung cancer cells." (PMID 24348855, 2014). "However, the pattern of Pygo2 expression in lung cancer was unknown and the correlation of Pygo2 expression with the clinicopathological factors of lung cancer had not been determined." (PMID 23865714, 2013).
ovarian carcinoma (5 papers, 2013 to 2024). A malignant neoplasm originating from the surface ovarian epithelium. "However, we found down regulation of PYGO2, which was founded to be up regulated in ovarian cancer." (PMID 23483081, 2013).
brain glioma (4 papers, 2016 to 2025). A malignant glioma that involves the brain. "Patients with high Pygo2 expression correlated with a higher risk of human brain glioma progression compared to patients with low Pygo2 expression (P < 0.001)." (PMID 26902498, 2016). "The high expression level of Pygo2 indicated a high risk for brain glioma oncogenesis." (PMID 26902498, 2016). "The abnormal expression of Pygo2 has a high risk to brain glioma oncogenesis." (PMID 26902498, 2016). "For instance, in the context of brain gliomas, the expression levels of Pygo2 have been found to correlate with the extent of tumor progression." (PMID 40771810, 2025). "Because the phosphorylation of Bcl-2 induced by PTX also plays a critical role in apoptotic decisions, we also studied the relationship between the Pygo2 expression level and the phosphorylation level of Bcl-2 in human brain glioma U-87MG and U251 cell lines." (PMID 28427190, 2017). "We found that over-expression of Pygo2 in human brain glioma significantly correlates with the age and the tumor grade by WHO, but not with the gender." (PMID 26902498, 2016). "By use of Kaplan–Meier analysis and survival curve, we also revealed correlation of Pygo2 abnormal expression with poor prognosis in human brain glioma patients." (PMID 26902498, 2016). "To investigate the prevalence of Pygo2 expression in human brain glioma and normal tissues, we analyzed the in situ localization of Pygo2 in 231 tissues from archived surgical samples." (PMID 26902498, 2016). "Overall, these data revealed that Pygo2 also plays important regulatory roles in the Wnt/β-catenin pathway in human brain glioma cell lines." (PMID 26902498, 2016). "Overall, our data showed that abnormal Pygo2 expression correlates with tumor progression and poor prognosis in human brain glioma." (PMID 26902498, 2016). "This research suggests that Pygo2 may be instrumental in the initiation and advancement of brain gliomas." (PMID 40771810, 2025). "We previously reported that Pygo2 was up-regulated in human brain glioma tissues and cell lines." (PMID 28427190, 2017). "Pygopus2 (Pygo2), which contains a Zn-coordinated plant homeodomain (PHD) finger domain, is critical for β-catenin-dependent transcriptional switches in normal and malignant tissues and is over-expressed in various cancers, including human brain glioma." (PMID 28427190, 2017).
gastric cancer (4 papers, 2019 to 2025). A primary or metastatic malignant neoplasm involving the stomach. "The relationship among Pygo2 expression and prognosis, immune microenvironment and immunotherapy effect was studied in 282 gastric cancer patients." (PMID 40771810, 2025). "Clinicopathological characteristics and staining patterns of Pygo2 in gastric cancer." (PMID 40771810, 2025). "It has been reported that PYGO2 could be a new biomarker for detecting drug resistance through overexpression of MDR1 in gastric cancer." (PMID 40034933, 2024). "PYGO2 plays a critical function in regulating the transcription process, as it can modulate multidrug resistance (MDR) transcription by binding to the MDR1 promoter sequence and inducing MDR1 activation in gastric cancer." (PMID 40034933, 2024).
prostate carcinoma (4 papers, 2021 to 2025). A carcinoma that arises from epithelial cells of the prostate gland. "In prostate cancer, it was observed that the expression of Pygo2 in cancer cells was negatively correlated with the infiltration of T cells." (PMID 40771810, 2025). "PYGO2 has recently been identified in functional genomics in vivo screens as an oncogenic driver of prostate cancer." (PMID 35204808, 2022). "Genetic analysis of large prostate cancer datasets has revealed that several co-activators of β-catenin-mediated transcriptional activity are amplified in prostate cancer, such as BCL9 and PYGO2." (PMID 35204808, 2022). "Interestingly, high PYGO2 expression has also been shown to positively correlate with earlier PSA biochemical recurrence, indicating PYGO2 may also prove to be a valuable predictive biomarker for prostate cancer." (PMID 35204808, 2022).
breast tumors (2 papers, 2014 to 2019). "Further investigations are required to analyze the interplay of Wnt1/BCL9-2/Pygo2 for the induction of ER+ breast tumors in vivo." (PMID 25149534, 2014). "Thus, BCL9-2 and its binding partner Pygo2 apparently drive breast tumor development in vivo by ß-catenin independent mechanisms." (PMID 25149534, 2014).
glioblastoma (2 papers, 2015 to 2016). The most malignant astrocytic tumor (WHO grade IV). "Pygo2 protein was strongly expressed in the nuclei of Glioblastoma tissues, which indicates endothelial cell hyperplasia, atypical proliferation, and increased karyokinesis." (PMID 26902498, 2016).
male infertility (2 papers, 2022 to 2024). The inability of the male to effect fertilization of an ovum after a specified period of unprotected intercourse. "In mice, mutations leading to reduced levels of Pygo2 or abolishing the binding ability of Pygo2 to H3K4me2/3 result in male infertility." (PMID 38892188, 2024). "This study was performed to investigate the correlation of some single nucleotide polymorphisms of PYGO2, DAZL, PRM1, and PRM2 genes with male infertility in idiopathic cases among the Iranian population." (PMID 36197138, 2022). "In this study, we tried to find the association of some SNPs of PYGO2, PRM1, PRM2, and DAZL genes with male infertility." (PMID 36197138, 2022).
non-small cell lung carcinoma (2 papers, 2013 to 2017). A group of at least three distinct histological types of lung cancer, including non-small cell squamous cell carcinoma, adenocarcinoma, and large cell carcinoma. "To address this question, we examined Pygo2 expression patterns and their prognostic significance in patients with non-small cell lung carcinoma (NSCLC)." (PMID 23865714, 2013).